CDK9 (cyclin dependent kinase 9)
Diseases named in the same sentence as CDK9 in open-access papers (continued):
Sharing a sentence is not in itself a finding about the gene and the disease.
cancer (continued). "In line with the idea that cancer cells require increased transcriptional elongation for their high turn-over metabolism, CDK9 has been shown to be dysregulated in several cancers to favor cancer cell proliferation, apoptosis resistance and spread." (PMID 34535764, 2022). "Cancer cells typically have compromised DNA damage response, which would selectively sensitize these malignant cells and save the normal cells from CDK9 inhibitors." (PMID 35164752, 2022). "Given the fact that CDK7 and CDK9 are more essential for cancer cell fitness relative to the other tCDKs, we focused on gene signatures enriched among their positive co-dependencies with potential oncogenic roles." (PMID 36577800, 2022). "In this study, we provide evidence at both the transcriptional and protein levels that the inhibition of CDK9 activity can boost the immunogenicity of cancer cells." (PMID 35708495, 2022). "Although the mechanism of action and anti-cancer efficacy of the CDK9 inhibitors have been validated both in vitro and in animal models, their clinical outcomes have not been satisfactory." (PMID 35383271, 2022). "We found that tCDKs have a wide range of effects on cancer cell viability, with CDK7 and CDK9 being the most essential across different cancer lineages, while other tCDKs display context-dependent essentiality that is independent of cancer type." (PMID 36577800, 2022). "In summary, newer generations of CDK9 inhibitors are already opening-up its untapped potential as an anti-cancer therapy and ongoing works in this direction are helping develop better, more selective inhibitors." (PMID 34062779, 2021). "More exacting pre-clinical trials are necessary to better understand the nuances in the functions of CDK9 between normal and cancer cells, to be able to specifically target the latter." (PMID 34062779, 2021). "Cyclin-dependent kinase 9 (CDK9), an important regulator of transcriptional elongation, is a promising target for cancer therapy, particularly for cancers driven by transcriptional dysregulation." (PMID 34066883, 2021). "Enhanced CDK9 activity, therefore, leads to poorer prognosis in many cancer types, offering the rationale to target it using small-molecule inhibitors." (PMID 34062779, 2021). "More recently a novel highly selective CDK9 inhibitor-21e, was shown to inhibit CDK9 activity (IC50 11 nM) in NSCLC cells as well as cell lines of other cancer entities." (PMID 34062779, 2021). "Given its pivotal functions, when CDK9 becomes overactive in many hematological and solid cancers there is a continuous production of short-lived proteins that maintain the survival of cancer cells." (PMID 34041038, 2021). "This article reviews the most recent CDK9 patent literature (2012–2020) related to small molecule inhibitors in cancer along with their selectivity profile and biological results in preclinical studies." (PMID 33632038, 2021). "Given that CDK9 plays a crucial role in regulating transcription elongation, inhibiting CDK9 can reduce the transcription of genes necessary for maintaining cancer cell survival." (PMID 34207158, 2021). "AbbVie published seven patent applications from 2014 to 2016 covering more than 13,600 derivatives of the pyrrolo[2,3-b]pyridine scaffold as CDK9 inhibitors targeting cancer." (PMID 33632038, 2021). "As has been mentioned in the previous sections, due to the high specificity of LDC000067 against CDK9, it has proved to be a valuable tool in pre-clinical studies against multiple and diverse cancer entities." (PMID 34062779, 2021). "The inhibition of CDK9’s activity holds the potential to be a highly effective anti-cancer therapeutic." (PMID 34062779, 2021).
cancer (continued). "Experiments with Osimertinib-resistant PC9 and AMG510 insensitive H23 and H358 KRASG12C cells show that CDK9 inhibitors elicit almost identical efficacy on the sensitive and resistant cancer cells." (PMID 34359807, 2021). "Since one of the major impediments in cancer therapy is the development of resistance, we examined if CDK9 inhibitors are capable of eliminating drug-resistant cells." (PMID 34359807, 2021). "As such, CDK9 represents an attractive target for cancer therapeutics, and there are great hopes that inhibition of CDK9 can be used to effectively and selectively restrict cell growth." (PMID 34146121, 2021). "Given the importance of CDK9 and Cyclin K in DNA damage repair, studies in cancer models have focused on inhibiting CDK9 to generate increased replication stress and facilitate cancer cell death." (PMID 34207158, 2021). "Recent studies have shown that CDK9 plays an oncogenic role in various malignant tumors such as osteosarcoma, colon cancer, and glioblastoma." (PMID 35071768, 2021). "The various CDK9 inhibitors, their target kinase (s), cancer entities they were tested against (includes pre-clinical trials where clinical trials were never performed) and their clinical trials (wherever performed)." (PMID 34062779, 2021). "Since, unlike LGR5-GFP, the OSCAR reporter does not rely on any cell type-specific promoter or activity, but instead reports low CDK9 activity it is likely to be generically useful for imaging and isolation of dormant cells in many tissue or cancer types." (PMID 34083536, 2021). "Patents were collected from world intellectual property organisation (WIPO), Espacenet and Scifinder databases using “CDK9” and “cancer” as keywords and combining the results." (PMID 33632038, 2021). "Since CDK9 was identified as a promising therapeutic opportunity in cancer, its inhibition has become a main strategy for large pharmaceutical companies, and a number of chemical motifs have been developed." (PMID 33632038, 2021). "One missing piece of knowledge in the CDK9 puzzle is a full validation of this target for cancer treatment." (PMID 34041038, 2021). "Bayer filed 10 patent applications during 2013–2018 covering 2-aminopyridines/pyrimidines as selective CDK9 inhibitors for cancer therapy." (PMID 33632038, 2021). "Most cancers overtly employ CDKs that serve as key regulators of transcription (e.g., CDK9) for a continuous production of short-lived gene products that maintain their survival." (PMID 34041038, 2021). "The Lead Discovery Centre claimed the 2-aminotriazine derivative 47 as a potent and selective CDK9 inhibitor for treatment of cancer." (PMID 33632038, 2021). "Meanwhile, a more advanced understanding of its biology is likely to pave the way for establishing a sounder basis for the future value of CDK9 inhibitors for cancer therapy." (PMID 34041038, 2021). "CDK9 was involved in cancer progression through BRD4-dependent recruitment of p-TEFb involving transcription of the MYC gene, and that MYC is a proto-oncogene that controls cell growth and cell cycle processes." (PMID 35087760, 2021). "This is particularly so for CDK9, a key regulator of transcription which is overtly employed by cancer cells for the constant production of short-lived proteins that maintains their survival." (PMID 34041038, 2021). "A clinical trial for the highly selective CDK9 inhibitor KB-0742 was even launched recently in January 2021 to treat MYC-amplified cancers and is currently enrolling patients with advanced solid tumors or non-Hodgkin’s lymphoma." (PMID 34207158, 2021). "These indicate that CDK9 is a promising cancer target, especially for cancers that are driven by transcriptional dysregulation." (PMID 34771669, 2021). "CDK9 inhibition has also been reported as a useful strategy for treating cancers with MYC overexpression." (PMID 34207158, 2021).
cancer (continued). "Cyclin-dependent kinase 9 (CDK9) plays a vital role in transcription through regulation of short-lived anti-apoptotic genes required for cancer cell survival." (PMID 33632038, 2021). "The authors claimed compound 68 as a CDK9 inhibitor for treatment of cancer, with a CDK9 IC50 value of 93.7 nM." (PMID 33632038, 2021). "Rather, many of the pathways that are impacted by CDK9 inhibition in the various cancers reflect the different pre-established gene expression profiles of their tissues of origin." (PMID 34207158, 2021). "In these cancer types, CDK9 regulates a plethora of cellular functions including proliferation, survival, cell cycle regulation, DNA damage repair and metastasis." (PMID 34062779, 2021). "Some studies found that selective CDK9 inhibitors had the potential to treat a variety of human diseases, including cancer." (PMID 34277564, 2021). "Dinaciclib was shown to drastically enhance EV-T killing effects on cancer lines that express good levels of death receptor (DR) 5, which are associated with suppression of CDK1, CDK9 and anti-apoptotic proteins." (PMID 32375399, 2020). "In some types of cancer including ovarian cancer, pancreatic cancer, breast cancer, and osteosarcoma, on the other hand, P-TEFb expression (CDK9 and/or CycT1) is aberrantly upregulated, resulting in global stimulation of P-TEFb-dependent transcription." (PMID 32075058, 2020). "This crucial function and the evidence that transcriptional programs are dysregulated in cancer made CDK9 an attractive target for anti-cancer therapies." (PMID 32903585, 2020). "We show that fadraciclib demonstrates improved kinase inhibitory potency in vitro against its primary CDK targets–CDK2 and CDK9 –as well as anti-cancer activity in in vitro and in vivo models." (PMID 32645016, 2020). "Fadraciclib preclinical pharmacology data support its therapeutic potential in CDK9- or CDK2-dependent cancers and as a rational combination with BCL2 inhibitors in hematological malignancies." (PMID 32645016, 2020). "This contrasts with dependency of cancer cell lines revealed following the genetic loss of CDK2 and particularly CDK9." (PMID 32645016, 2020). "CDK9 was involved in cancer progression through the BRD4-dependent recruitment of p-TEFb for the transcription of the MYC gene, which is a proto-oncogene controlling cell growth and cell cycle progression." (PMID 32848135, 2020). "This made the anti-apoptotic protein an attractive cancer therapeutic target and several classes of agents, including CDK9 and direct MCL1 inhibitors, are now being tested in clinical trials [reviewed in refs: 61,62]." (PMID 32645016, 2020). "Overall, additional future preclinical research is needed to better understand how CDK9 functions in normal and cancer cells to ultimately define the therapeutic applicability of CDK9 inhibitors as single or adjuvant anti-cancer molecules." (PMID 32903585, 2020). "In this review, we briefly describe the roles of CDK9 in transcriptional processes and summarize the last insights on natural products as CDK9 inhibitors in cancer." (PMID 32903585, 2020). "We show that CDK9 inhibition or knockdown can have a profound effect on the levels of MDM4 oncoprotein in cancer cells overexpressing MDM4 and human pluripotent stem cells, with a minimal impact on MDM2 expression." (PMID 32934219, 2020). "The main anti-cancer mechanism of wogonin and other related flavones such as apigenin, chrysin, and luteolin, has been ascribed to their ability to selectively inhibit CDK9 activity by binding the ATP-binding pocket." (PMID 32903585, 2020). "We previously reported a lead compound from this series, CCT068127, with reduced metabolism, enhanced selectivity towards CDK2 and CDK9 and superior therapeutic activity against human cancer cells." (PMID 32645016, 2020).
cancer (continued). "More recently, we constructed an H-1PV silencer expressing shRNAs targeting CDK9 (H-1PV sil-shCDK9), whose expression and activity are often dysregulated in cancer cells, thus contributing to cancer development." (PMID 31216641, 2019). "The Cdc7/Cdk9 inhibitor is a strong candidate as a cancer therapeutic, but its effect on the immune system poses a problem for clinical applications." (PMID 31402912, 2019). "HNRNPK has been reported to associate with CDK9 and XRN2 in cancer cells to potentially regulate transcription elongation and termination, respectively." (PMID 31519929, 2019). "In our experiments, T cells were sensitive to Cdc7/Cdk9 inhibition in the range of concentrations similar to those reported for cancer cells." (PMID 31402912, 2019). "Significant differentiation effects were detected for Menin-MLL, DOT1L, and DHODH inhibitors, whereas BET and CDK9 inhibitors primarily induced apoptosis in AML/ALL cancer models." (PMID 31253180, 2019). "CDKI‐73, one of the most potent and pharmacologically superior CDK9 inhibitors, has demonstrated excellent anti‐tumour efficacy against several types of cancers." (PMID 31398271, 2019). "Multiple studies using small molecule inhibitors and RNA interference have demonstrated that oncogenic transcription driven by CDK9 increases the survival and proliferation of cancer cells and hence is continuously targeted for cancer treatment." (PMID 31398271, 2019). "CDKI‐73 effectively induced cancer cell death and displayed a robust CDK9‐targeted mechanism of action both in vitro and in vivo." (PMID 31398271, 2019). "The CDK9-related pathway has emerged as a prioritized target for cancer therapy across a range of tumor types." (PMID 29471852, 2018). "Consultation of cancer genome repositories such as cBioPortal, the COSMIC database and TumorPortal reveals a variety of other missense mutations within CDK–cyclins in the context of cancer (e.g. R168C in CDK5, R86Q CDK9, R378G in cyclin A2)." (PMID 30185601, 2018). "Specifically in TNBC, inhibition of CDK9 has been linked to decreased cyclin B1 and MYC, and treatment with dinaciclib resulted in G2/M phase arrest and cancer cell apoptosis." (PMID 29137393, 2017). "The other distinct class includes CDK inhibitors that are more selective for CDK1 and CDK2 as well as the transcriptional CDKs (CDK5, CDK7, and CDK9), and these drugs are being more widely studied in cancers including triple-negative breast cancer." (PMID 28107181, 2017). "Cyclin‐dependent kinase 9 (CDK9) stimulates the production of abundant prosurvival proteins, leading to impaired apoptosis of cancer cells." (PMID 28940993, 2017). "CDK9 interacts with many transcription factors (TFs) and regulates the expression of antiapoptotic proteins for the survival of cancer cells." (PMID 28940993, 2017). "Small molecule inhibitors of CDK9 have been shown to induce apoptosis in cancer cells by suppressing Mcl-1." (PMID 28520795, 2017). "CDK9 inhibition has been shown to synergise with TRAIL treatment to induce apoptosis in TRAIL-resistant cancer cells." (PMID 28326166, 2017). "Dinaciclib, a potent CDK2 inhibitor (as well as CDK1, CDK5, and CDK9 inhibitor) that is currently in clinical trials for several cancers, was used to target the cyclin E/CDK2 pathway." (PMID 28107181, 2017). "For instance, previous investigations have demonstrated that loss of HMGCR, CDK9, ARK5, or CSNK1e gene is highly detrimental for the survival of cancer cells exhibiting c-Myc activation." (PMID 29207593, 2017). "Because CDK9 inhibition suppresses transcription of antiapoptotic proteins, several CDK9 inhibitors are currently in clinical development for the treatment of cancer." (PMID 28817720, 2017). "The relevance of CDK2, CDK7, and/ or CDK9 as crucial SNS-032 drug targets differs between different cancer cell types." (PMID 27517323, 2016).
cancer (continued). "Nevertheless, inhibition by small molecules inhibiting Cdk5 and additionally Cdk1, Cdk2, Cdk7, and Cdk9 have shown promising effects in cancer/angiogenesis." (PMID 26755662, 2016). "In contrast, recent work in cancer cells and flies showed that depletion of Paf1 led to dramatic enhancement of CDK9 recruitment, coincident with release of paused PolII and increased phosphorylation of Ser2 on the CTD." (PMID 26765774, 2016). "These compounds included AT7519, which is a multi-CDK inhibitor with a very low IC50 (<10nM) for CDK9, and is currently in phase-II clinical trials for several cancers." (PMID 26812885, 2016). "CDKs have received considerable attention as major targets for anti-cancer drugs, and more than 20 compounds that inhibit CDK9 and other CDKs have entered in different phases of clinical trials." (PMID 26812885, 2016). "CDK9 inhibition is currently being evaluated in pre-clinical and clinical studies for the treatment of a number of different cancers, mainly in combination with other chemotherapeutic agents." (PMID 26542022, 2015). "Dinaciclib, a novel small molecule inhibitor of CDK1, CDK2, CDK5 and CDK9, is assessed in clinical trials for the treatment of several types of cancers." (PMID 25962959, 2015). "It has recently been shown that a novel CDK9 inhibitor inhibits RNA pol II phosphorylation and Mcl-1 transcription, thus showing strong anti-cancer therapeutic activity." (PMID 26720004, 2015). "Currently, CDK9 inhibitors are being explored as anti-cancer therapies because the kinase stabilises the P-TEFb complex and drives PolII transcription elongation of various oncogenic mRNAs." (PMID 26501340, 2015). "Because of this compensatory mechanism, our data demonstrate that the simultaneous inhibition of both CDK9's catalytic activity and MYC's expression or function causes synergistic induction of growth arrest and apoptosis of cancer cells." (PMID 26083714, 2015). "All this taken together, CDK9 is an important target kinase that control Mcl-1 stability and turnover in cancer cells." (PMID 26720004, 2015). "CDK9 activity is deregulated in numerous malignancies and human pathologies, and is a target for pharmacological inhibition for cancer therapies." (PMID 25992613, 2015). "Within this panel, we identified cyclin-dependent kinase 9 (CDK9) as responsible for TRAIL resistance of cancer cells." (PMID 24362439, 2014). "Combination of CDK9 inhibition with TRAIL effectively induced apoptosis even in highly TRAIL-resistant cancer cells." (PMID 24362439, 2014). "CDK9 inhibition as an effective anti-cancer strategy has gained strong support in recognizing that cancer cells rely on the production of short-lived apoptosis regulators and mitotic regulatory kinases for survival." (PMID 25277198, 2014). "As such, CDK9 inhibitor drug candidate CDKI-73 should have a major impact on these pathways in human cancers." (PMID 25277198, 2014). "Having established that CDK9 inhibition efficiently sensitizes cancer cell lines to TRAIL-induced apoptosis, we next addressed which molecular changes are responsible for this effect." (PMID 24362439, 2014). "Based on our results, we propose CDK9 inhibition as an effective means to overcome TRAIL resistance in a cancer-selective manner." (PMID 24362439, 2014). "using an shRNA strategy, triggered CLL cell apoptosis confirming cdk9 as a potential anti-cancer therapeutic target." (PMID 24495868, 2014). "CDK2 siRNA silencing and inhibition of CDK2 kinase activity using a CDK1, CDK2 and CDK9 inhibitor (AZD5438) resulted in significantly higher reduction in survival of cancer cells harbouring CCNE1 gene amplification." (PMID 22433433, 2012). "Increasing evidence highlights CDK9’s involvement in transcriptional addiction in cancer." (PMID 41505030, 2026). "CDK9 has thus been deemed an attractive target for new cancer therapies." (PMID 40954203, 2026).